VRK2 (VRK serine/threonine kinase 2)
Description:
Serine/threonine kinase that regulates several signal transduction pathways. Isoform 1 modulates the stress response to hypoxia and cytokines, such as interleukin-1 beta (IL1B) and this is dependent on its interaction with MAPK8IP1, which assembles mitogen-activated protein kinase (MAPK) complexes. Inhibition of signal transmission mediated by the assembly of MAPK8IP1-MAPK complexes reduces JNK phosphorylation and JUN-dependent transcription. Phosphorylates BANF1 and disrupts its ability to bind DNA and reduces its binding to LEM domain-containing proteins. Down-regulates the transactivation of transcription induced by ERBB2, HRAS, BRAF, and MEK1. Blocks the phosphorylation of ERK in response to ERBB2 and HRAS. Can also phosphorylate the following substrates that are commonly used to establish in vitro kinase activity: casein, MBP and histone H2B, but it is not sure that this is physiologically relevant.
Tractability: Small molecule: a structure with a bound ligand is known; a high-quality ligand is known; it belongs to a druggable protein family. Antibody: UniProt predicts a signal peptide or a membrane-spanning region. PROTAC: ubiquitination databases record sites on it; its protein half-life has been measured; a small molecule that binds it is known.
Target class: Enzyme
Gene: Protein-coding gene on chromosome 2 (57,907,606 to 58,164,001, forward strand). Ensembl gene ENSG00000028116.
Subcellular location: Cytoplasm (Isoform 1); Endoplasmic reticulum membrane; Mitochondrion membrane; Nucleus envelope; Cytoplasm (Isoform 2); Nucleus
Subcellular location (Human Protein Atlas): Endoplasmic reticulum
Pathways (Reactome):
Signal Transduction: RAC1 GTPase cycle; RAC2 GTPase cycle; RAC3 GTPase cycle; RHOD GTPase cycle; RHOG GTPase cycle
Cell Cycle: Initiation of Nuclear Envelope (NE) Reformation; Nuclear Envelope Breakdown
Gene Ontology:
Molecular function: protein binding; protein domain specific binding; protein kinase binding; protein serine kinase activity; protein serine/threonine kinase activity; ATP binding; protein kinase activity
Biological process: cellular response to oxidative stress; protein autophosphorylation; regulation of interleukin-1-mediated signaling pathway; regulation of MAPK cascade; DNA damage response; protein phosphorylation
Cellular component: cytoplasm; endoplasmic reticulum; endoplasmic reticulum membrane; mitochondrial membrane; nucleus; protein-containing complex; nuclear envelope; membrane; organelle envelope
Genetic constraint (gnomAD): Loss-of-function variants: 37 observed, 42.78 expected, observed/expected ratio (o/e) 0.86, 90% interval 0.66 to 1.14. The upper end of that interval is the gene's LOEUF score, 1.14, which puts it in group 4 of 6, group 1 being the genes least tolerant of losing a copy. Missense variants: 609 observed, 521.74 expected, observed/expected ratio (o/e) 1.17, 90% interval 1.09 to 1.25. Synonymous variants: 189 observed, 177.57 expected, observed/expected ratio (o/e) 1.06, 90% interval 0.94 to 1.2.
Homologues: Orthologues: chimpanzee VRK2 (99% identical), macaque VRK2 (94% identical), rabbit VRK2 (82% identical), guinea pig VRK2 (81% identical), pig VRK2 (81% identical), dog VRK2 (76% identical), mouse Vrk2 (69% identical), rat Vrk2 (68% identical), tropical clawed frog vrk2 (41% identical), zebrafish vrk2 (40% identical), Drosophila melanogaster ball (31% identical), Caenorhabditis elegans vrk-1 (25% identical), and 63 more. Paralogues in human: VRK1 (37% identical), VRK3 (23% identical), TTBK2 (21% identical), TTBK1 (21% identical), CSNK1D (20% identical), CSNK1E (20% identical), CSNK1G3 (19% identical), CSNK1G2 (19% identical), CSNK1A1 (19% identical), CSNK1A1L (18% identical), CSNK1G1 (18% identical), CDC7 (11% identical).
Diseases named in the same sentence as VRK2 in open-access papers:
VRK2 is named in the same sentence as 52 diseases in open-access papers, as found by Europe PMC text mining. Sharing a sentence is not in itself a finding about the gene and the disease. The quoted sentences say what the papers report.
schizophrenia (15 papers, 2013 to 2026). A major psychotic disorder characterized by abnormalities in the perception or expression of reality. "Vaccinia‐related kinase 2 (VRK2) is a prominent genetic risk factor for neurodevelopmental disorders (NDDs), including schizophrenia and epilepsy, which are characterized by cognitive and behavioral impairments." (PMID 41263186, 2026). "Common sequence variations in the VRK2 gene contribute to genetic risk for various psychiatric diseases including schizophrenia and major depressive disorder." (PMID 32583282, 2020). "A number of SNPs in the region of VRK2 have previously been associated with schizophrenia, implicating it in the development of the disease." (PMID 31616042, 2020). "The effect direction is consistent with previous studies that have linked decreased VRK2 expression to neurological disorders including schizophrenia." (PMID 32773033, 2020). "In genome wide association studies in humans, VRK2 has been consistently associated with psychiatric and neurodegenerative disorders such as schizophrenia, major depressive disorder and genetic generalized epilepsy." (PMID 32822435, 2020). "In fact, sequence variants in the VRK2 gene are robustly associated with schizophrenia, and also with depression, bipolar disorder, and epilepsy." (PMID 32583282, 2020). "VRK2 is a serine/threonine kinase important in several signal transduction cascades, and variants near VRK2 are associated with schizophrenia and epilepsy." (PMID 27494321, 2016). "Although the exact mechanism should be unveiled in further studies, the association of VRK2 with schizophrenia has been replicated in GWASs and a meta-analysis." (PMID 25079070, 2014). "Recently conducted GWASs showed the significant association of rs2312147, located about 50 kb upstream of VRK2, and schizophrenia in Asians as well as Europeans." (PMID 25079070, 2014). "In conclusion, the present study is the first to demonstrate an association between altered WM connectivity and rs2312147 (VRK2) in patients with schizophrenia." (PMID 25079070, 2014). "Recent genome-wide association studies of schizophrenia reported a novel risk variant, rs2312147 at vaccinia-related kinase 2 gene (VRK2), in multiple Asian and European samples." (PMID 25079070, 2014). "An association between FA values and VRK2 rs2312147 genotypes was found only in the schizophrenia group." (PMID 25079070, 2014). "Notably, common risk variants of Vrk2, such as rs2312147 and rs3732136 are associated with altered cortical and subcortical brain function in schizophrenia, while rs1302641 has been linked to epilepsy." (PMID 41263186, 2026). "Variants in human VRK2 have also been associated with schizophrenia and major depressive disorder." (PMID 41143948, 2025). "Of relevance to substance use disorders, Vrk2 was a human GWAS hit for opioid and cannabis use disorders, was associated 18 times each with schizophrenia and neuroticism measures, seven times with alcohol consumption or alcohol use disorder, and five times in smoking-related GWAS." (PMID 41143948, 2025). "In addition, GWAS studies have shown associations between VRK2 and size of the cerebral cortex, epilepsy, depression, bipolar disorder, anorexia nervosa, schizophrenia, autism spectrum disorder, and post-traumatic stress disorder." (PMID 37792698, 2023). "Moreover, the association of another variant in the VRK2 promoter region, rs2312147, with white matter volume in healthy subjects, and white matter connectivity in schizophrenia patients implicates this locus in aberrant brain development." (PMID 31616042, 2020). "It has recently been reported that in the brain, Vrk2 expression is restricted to microglia If this were verified, this would be of some significance for understanding the causes of schizophrenia, as it would unequivocally implicate microglial dysfunction in disease aetiology." (PMID 32583282, 2020).
schizophrenia (continued). "Further work is required to determine whether variation in VRK2 either has independent associations with both sleep and schizophrenia or whether there is some causal link between sleep duration and pattern and schizophrenia and epilepsy." (PMID 27494321, 2016). "The highest three scoring genes have all been previously shown to play important roles in the brain: ACTL6A, a chromatin remodeling factor which is required for the development of neural progenitors; VRK2, a gene implicated in schizophrenia; and the Huntington’s gene, HTT." (PMID 25970446, 2015). "Considering the possible role of VRK2 in apoptosis, it can be assumed that the WM connectivity abnormalities associated with VRK2 rs2312147 genotypes may be shown only in patients with schizophrenia." (PMID 25079070, 2014). "Our findings suggest that VRK2 rs2312147 may play a crucial role in the pathophysiology of schizophrenia in association with cognitive function." (PMID 25079070, 2014). "There is also evidence that whole blood VRK2 mRNA levels are lower in schizophrenia patients than healthy controls." (PMID 31616042, 2020). "Among them, rs2312147 [C], located ∼50 kb upstream of vaccinia-related kinase 2 (VRK2), was identified as a novel risk of single nucleotide polymorphism (SNP) associated with schizophrenia in Europeans, and Asians." (PMID 25079070, 2014). "Our data may provide evidence for the effect of VRK2 on WM connectivity in patients with schizophrenia." (PMID 25079070, 2014). "The role of VRK2 in determining the magnitude of the stress response induced by hypoxia or modulation of interleukin-1β transcriptional response might implicate a probable connection to the pathophysiology of schizophrenia." (PMID 25079070, 2014). "Our data support the hypothesis that VRK2 rs2312147 may affect WM connectivity responsible for transmitting information, in relation to cognitive function assessed by DST performance in patients with schizophrenia." (PMID 25079070, 2014). "However, this should be interpreted with caution since the effect of VRK2 on the brain structure of patients with schizophrenia has not been investigated until now." (PMID 25079070, 2014). "Of interest, the VRK2 region (2p16.1) was identified in the previous sample after including a large schizophrenia replication sample, and the ITIH4 region (3p21.1), ANK3 (10q21) and CACNA1C (12p13.3) were discovered previously in the same, combined schizophrenia and bipolar disorder sample." (PMID 23637625, 2013).
epilepsy (9 papers, 2014 to 2026). A brain disorder characterized by episodes of abnormally increased neuronal discharge resulting in transient episodes of sensory or motor neurological dysfunction, or psychic dysfunction. "Meanwhile, another GWAS revealed the association between the SNPs around VRK2 (rs13026414 and rs2717068) and genetic epilepsies, which may suggest VRK2-associated neurodevelopmental alterations." (PMID 25079070, 2014). "Since apoptosis plays a crucial role in the development of both COVID-19 and epilepsy, VRK2 may contribute to the disease mechanism through its apoptosis mechanism." (PMID 37781245, 2023). "In addition, several other studies have reported the possibilities of the relation between VRK2 and neurodevelopmental abnormalities, e.g., cortical dysplasia and epilepsies." (PMID 25079070, 2014). "Nine shared genetic loci and six pleiotropic genes, including SCN1A, PGBD1, ZKSCAN3, ZKSCAN4, VRK2, and ZSCAN23, have been identified between epilepsy and psychiatric disorders." (PMID 41733899, 2026). "Of these, 6 genes were found to be shared between COVID-19 and epilepsy, including SMEK2, PNPT1, EFEMP1, CCDC85A, VRK2, and BCL11A, all located on chromosome 2." (PMID 37781245, 2023). "Further, FUMA analysis identified six overlapping genes, including SMEK2, PNPT1, EFEMP1, CCDC85A, VRK2, and BCL11A, shared between COVID-19 and epilepsy." (PMID 37781245, 2023).
breast carcinoma (7 papers, 2012 to 2023). "In contrast, another study found that low VRK2 levels are associated with the abnormal MEK/ERK signaling seen in breast cancer; thus, VRK2 has a complex signaling role in cancer." (PMID 35911672, 2022). "Amino acid variation of VRK2 affects tumor growth by regulating dysbindin and cyclin D in mouse and human breast cancer tissue." (PMID 38186576, 2023). "It has also been observed that in patient samples, VRK2 level was elevated in breast cancer tissue compared to normal breast tissue." (PMID 38186576, 2023). "A comparison of VRK2 cDNAs isolated from breast cancer tissues and normal adjacent tissues showed that the frequency of c.499 = A in the mRNA sequence increased in cancer tissues without concomitant changes in the DNA sequence." (PMID 38186576, 2023). "In this study, we identified a novel RNA editing site in VRK2 that is altered in breast cancer cells and tissues." (PMID 38186576, 2023). "In breast cancer, VRK2 has been found to facilitate tumor cell invasion through phosphorylating transcription factor NFAT1 to increased COX2 expression." (PMID 35911672, 2022). "By contrast, data related to VRK2 expression identify a subgroup of primary high-grade astrocytomas with a better prognosis, and results obtained from 136 cases of human breast carcinoma showed that VRK2 downregulation contributes to breast cancer phenotype." (PMID 27456229, 2016). "This is consistent with the role of high VRK2 level in breast cancer, in which also correlates with tumors having a better prognosis, those that are estrogen and progesterone receptor positive and ERBB2 negative." (PMID 24079673, 2013). "So, we tested whether VRK2 regulates dysbindin and cyclin D in breast cancer cells using Western blot analysis." (PMID 38186576, 2023). "Additionally, the isoleucine form of VRK2 exhibited a greater increase in breast cancer tissue." (PMID 38186576, 2023). "Sixteen understudied kinases showed strong variance between TNBC and HER2/luminal breast cancer, with higher-ranked understudied kinases being DAPK3, ADCK1, MRCKA (CDC42BPA), STK17A, DMPK and VRK2." (PMID 29643987, 2018). "The expression of VRK1 and VRK2 as well as estrogen receptor and ERBB2 were determined in a panel of eight human breast cancer cell lines, including four of each type, luminal or basal." (PMID 24731990, 2014). "In addition, VRK2 phosphorylates the nuclear factor of activated T cells 1 (NFAT1) and modulates breast cancer cell invasion through elevated expression of cyclooxygenase 2 (COX2)." (PMID 38186576, 2023). "Kinases BUB1, CHEK1, IRAK1, TTK, RYK, and VRK2, identified in this study, for example, have been reported to be highly overexpressed in ER-negative breast tumors and were critical for the growth of either ER-negative only or both ER-positive and -negative breast cancer cells." (PMID 22309939, 2012).
depression (7 papers, 2020 to 2025). "Using luciferase reporter gene assays and eQTL analyses, the depression risk allele of rs2678907 decreased enhancer activities and predicted lower VRK2 mRNA expression, which is consistent with the observations of reduced VRK2 level in the patients with major depression compared with controls." (PMID 37452335, 2023).
glioblastoma (6 papers, 2013 to 2026). The most malignant astrocytic tumor (WHO grade IV). "Recently VRK1 was shown as a synthetic lethal target in VRK2-deficient glioblastoma and more globally in VRK2-promoter methylated cancers of the central nervous system, including DMG." (PMID 37886173, 2023). "Vaccinia-related kinase 1 (VRK1) is a promising therapeutic target in gliomas and glioblastomas where VRK2 is silenced by promoter methylation, rendering VRK1 essential for accurate nuclear envelope reassembly following mitosis." (PMID 41796804, 2026). "Targeting VRK1 in glioblastoma cells, neuroblastomas, and pediatric gliomas, in which VRK2 has been eliminated or silenced by VRK2-promoter methylation cells, is a potential synthetic lethality strategy in these tumors." (PMID 38753965, 2024). "Targeting VRK1 has been shown to be a suitable target in glioblastomas in which the VRK2 gene is silenced." (PMID 37179361, 2023). "For this aim the expression and subcellular localization of VRK1 and VRK2 proteins was determined in three glioblastoma cell lines, A172, LN18 and LN229 by immunofluorescence, and the pattern detected was similar to that observed in astrocytoma biopsies." (PMID 24079673, 2013).
astrocytoma (4 papers, 2013 to 2022). "This association of VRK2 expression to a better prognosis in malignant astrocytomas is likely to be associated to the roles that VRK2 plays in the modulation of mitogenic, stress or apoptosis signaling." (PMID 24079673, 2013). "Furthermore, survival analysis showed that high levels of VRK2 were significantly associated with longer survival in high-grade astrocytomas independently of age or treatment of patients." (PMID 24079673, 2013). "VRK2 protein expression was significantly associated with survival in high-grade astrocytomas." (PMID 24079673, 2013). "Clinically, VRK1 expression has been associated with high grade and poor prognosis in patients with glioma, whereas VRK2 expression is correlated with improved survival in high-grade astrocytoma." (PMID 36040810, 2022). "Inhibition of proliferative responses by the knockdown of VRK2 is consistent with another report, indicating that higher levels of VRK2 expression are present in a subgroup of primary high-grade astrocytoma cells." (PMID 29872222, 2018). "In summary, in this work we have identified the potential value of VRK2 expression as marker of a better prognosis in astrocytomas." (PMID 24079673, 2013). "VRK1 and VRK2 (Vaccinia-related kinase-1, -2) expression, as well as proliferation markers, were determined in a tissue microarray containing 105 primary astrocytoma biopsies." (PMID 24079673, 2013). "High levels of VRK2 protein is an indicator of a better prognosis in primary high-grade astrocytomas." (PMID 24079673, 2013). "VRK1 expression only correlated with p63 expression in both low and high-grade astrocytomas, while VRK2 expression correlated with ki67 levels only in high-grade astrocytomas." (PMID 24079673, 2013). "Next, it was determined if the growth rate of these three astrocytoma cell lines was in accordance with their EGFR/VRK2 ratio." (PMID 24079673, 2013). "High VRK2 protein levels identified a subgroup of astrocytomas that had a significant improvement in survival." (PMID 24079673, 2013). "In high-grade astrocytomas, VRK2 expression constitutes a good prognostic marker for patient survival." (PMID 24079673, 2013). "VRK2 protein level and tumor grade presented a positive correlation, thus in high-grade astrocytomas its level was significantly higher than in low-grade astrocytomas." (PMID 24079673, 2013). "The potential effect of VRK2 was studied by analyzing the growth characteristics of astrocytoma cell lines with different EGFR/VRK2 protein ratios." (PMID 24079673, 2013). "The expression of VRK1 and VRK2 proteins was determined in 105 astrocytomas." (PMID 24079673, 2013). "Furthermore, multivariate Cox model revealed that VRK2 expression, age and treatment were statistically significant independent predictors of high-grade astrocytoma survival." (PMID 24079673, 2013). "Thus, high VRK2 expression might reduce the strength of the mitogenic signals and contribute to a reduced growth rate as detected in the astrocytoma cell line with higher VRK2 relative level." (PMID 24079673, 2013). "High-grade astrocytomas overexpress high VRK1 and VRK2 RNA and protein levels (this work)." (PMID 24079673, 2013). "However, none of these alterations were related to VRK1 or VRK2 expression in astrocytomas, suggesting that these proteins could be involved in astrocytoma pathogenesis by different mechanisms." (PMID 24079673, 2013).